INS (insulin)
Diseases named in the same sentence as INS in open-access papers (continued):
Sharing a sentence is not in itself a finding about the gene and the disease.
diabetes (continued). "Insulin also preventsNrf2 stimulation of Agt expression via hnRNP F/Kexpression in diabetes." (PMID 28324005, 2017). "Another recent study in non-obese individuals at risk for diabetes demonstrated a negative association between baseline adiponectin and change in 2-hr plasma glucose, fasting insulin, HOMA-IR and HOMA- β." (PMID 28846711, 2017). "Median years of diabetes-free duration in women who had taken insulin was 2.1 years." (PMID 28491872, 2017). "The limitation of this study is that we did not investigate: 1) the erectile function of the rats at the different time points after diabetes induction; 2) if insulin treatment at 3 weeks after diabetes induction can fully prevent the structural changes of penile components." (PMID 28338308, 2017). "Generation of reactive oxygen species (ROS) secondary to hyperglycemia may lead to increased oxidative stress in β-cells which cause β-cell dysfunction and other long-term complications of diabetes because of insulin secretion and/or its function impairment." (PMID 29682485, 2017). "Scenario 2: Proportion of people with diabetes using insulin: 20%." (PMID 29163935, 2017). "One study conducted with a sample of Americans with diabetes mellitustaking insulin verified that weak correlations found for some items suggested that thescale could have more than one dimension." (PMID 28146182, 2017). "IR which generally precedes diabetes is a pathological condition in which the capacity of cells to respond to normal levels of insulin declines thus forcing the body to produce more and more insulin to be able to prevent hyperglycemia." (PMID 29299040, 2017). "A video game called Koodak-e-Tavana was designed to teach children about diabetes and insulin injections and aimed at reducing fear and anxiety; this study is one of the few involving children in the first step of the process that identifies needs and tasks which should be included in the game." (PMID 30291061, 2017). "Insulin, produced in pancreatic beta cells, plays a central role in modulating blood glucose metabolism, and insulin resistance is one of the characteristic of diabetes." (PMID 28496408, 2017). "In other GDM cohorts not selected for PCOS, insulin therapy has been associated with 3–5-fold higher risk of postdelivery diabetes compared to no insulin therapy." (PMID 29423416, 2017). "Therefore, our study aimed to assess the effect of a commercially available bee honey (1 g/kg/day for 4 weeks) on the concentrations of blood glucose, insulin and leptin and body weight in normal rats and rats with streptozotocin-induced diabetes." (PMID 28127544, 2017). "In addition, a sum up of 126 stroke patients were observed to combine with diabetes, among which 22.22% (28/126)patients received insulin treatment, and 59.5%(75/126) received hypoglycemic drugs." (PMID 28978089, 2017). "A total of 408 T1D or T2D users were excluded from the sample because they had either no medication data or because the medications logged or scheduled were inconsistent with their stated diabetes type (eg, T1D on metformin or sulfonylurea, T2D setting an auto basal insulin)." (PMID 30291059, 2017). "The data presented shows the relationship between pre-existing insulin secretagogues use, growth factor profiles at the time of breast cancer diagnosis and subsequent cancer outcomes in women diagnosed with breast cancer and type 2 diabetes mellitus." (PMID 28289695, 2017). "In addition to housekeeping genes, expression levels of SIGLECs were normalized to cell specific markers of β- and α-cells i.e. insulin and glucagon, to account for the changes in their mass in individuals with diabetes." (PMID 28378743, 2017). "Consequently, the failure of β-cells occurs in response to elevated insulin levels and thus elevated blood glucose which results in insulin insufficiency and overt diabetes." (PMID 29157234, 2017).
diabetes (continued). "A subsequent document published in 2015, Australian Credentialled Diabetes Educators and Prescribing of Insulin and Glucose Lowering Agents, further detailed the actions required to progress ADEA’s ambition to extend the scope of practice of CDEs to include non-medical prescribing." (PMID 28702089, 2017). "The data presented here shows the relationship between pre-existing use of insulin secretagogues in women diagnosed with breast cancer and type 2 diabetes mellitus, the GM-CSF, G-CSF and IL-7 cytokine profiles at the time of breast cancer diagnosis, and subsequent cancer outcomes." (PMID 28275660, 2017). "Thus, the goal of diabetes treatments should be to manage the balance of insulin resistance and insulin secretion, especially in Asians." (PMID 29104217, 2017). "Also, high concentrations of hydrogen peroxide directly with the phosphatidylinositol-3-kinase dependent pathway induce insulin signaling leading to insulin resistance prior to the onset of diabetes." (PMID 28497094, 2017). "Our study showed that neither honey nor insulin improved the loss in body weight induced by diabetes when compared to non-diabetic rats." (PMID 28127544, 2017). "Indeed, recent work also demonstrates that bariatric surgery promotes better glycaemic control in individuals with short‐duration vs. long‐duration diabetes 2 years after bariatric surgery because of insulin secretion 28 and/or insulin sensitivity." (PMID 28706732, 2017). "Currently, the clinical treatment of diabetes involves medication and insulin injection." (PMID 28758131, 2017). "Insulin was associated with a higher degree of severity because patients believed it was prescribed when the diabetes was not responding to other forms of treatment." (PMID 28405339, 2017). "He reckoned that the signal cross-talk between hypothalamic corticotrophin-releasing factor (CRF) system and insulin might be impaired, while fluoxetine treatment adjusting that system potentially prevented or healed depression and comorbid diabetes." (PMID 29084550, 2017). "For diabetes, therapeutic strategies comprise lifestyle optimization, sulfonylurea, glucagon-like peptide 1 analogues, dipeptidyl peptidase IV inhibitors as well as exogenous insulin." (PMID 28405347, 2017). "Transplantation of insulin-producing cells is considered an important diabetes therapy." (PMID 28747214, 2017). "This study aims to assess the insulin injection practice of patients with diabetes." (PMID 29333459, 2017). "Diabetes mellitus is a commonly metabolic syndrome that occurs because either the beta islet of pancreas does not produce enough insulin or the body cannot effectively utilize insulin." (PMID 28100206, 2017). "This ability of digestive enzymes (amylase) to reduce post-prandial hyperglycaemia in an insulin-independent manner could aid in preventing the development of obesity and diabetes." (PMID 28819193, 2017). "ER stress can be elicited by lipotoxicity and an increased demand for insulin in diabetes." (PMID 28102311, 2017). "Type 2 diabetes mellitus (T2DM) is a chronic and progressive disease that is strongly associated with hyperglycemia (high blood sugar) related to either insulin resistance or insufficient insulin production." (PMID 28934129, 2017). "We also found no strong evidence that insulin treatment is associated with clinicopathological subtypes; though the poor-prognosis tumors were more often occurring in premenopausal women with diabetes not using insulin and in type 1 diabetes insulin users." (PMID 28076434, 2017). "Furthermore, bromocriptine, a dopamine agonist that is well known to suppress serum PRL levels, has been shown to effectively improve insulin sensitivity, and has been approved for the treatment for type 2 diabetes mellitus in the United Sates." (PMID 28384295, 2017).
diabetes (continued). "Moreover, in diabetes, alteration of insulin signalling determines less IDE production, resulting in reduction of Aβ degradation; the process definitely leads to abnormal Aβ accumulation in the brain." (PMID 28656154, 2017). "Deterioration of β-cell function and insulin secretion are prior to clinical diabetes." (PMID 29089472, 2017). "An elevated HbA1c was also associated with frequent NLC, as were diabetes and fasting glucose (but not insulin), and the former variable was present after overall health was removed from the stepwise regression." (PMID 28586374, 2017). "The result obtained here indicated that the mean specific activity of Na+, K+ -ATPase of healthy individuals are higher than individuals with diabetes of the same age group and gender, which might be due to the insulin level." (PMID 29937894, 2017). "Diabetes mellitus (DM) is an autoinflammatory syndrome that is a collection of many disorders such as hyperglycemia, dyslipidemia, insulin resistance, impaired beta-cell functioning, and insulin secretion." (PMID 28422066, 2017). "From ours and from the previous results, we could assume that instability in metabolic parameters, such as glucose, BP or cholesterol levels could deteriorate insulin secretion and contribute to the development of atherosclerosis and diabetes." (PMID 28545051, 2017). "Insulin is susceptible to glycation by glucose, D-ribose and other highly reactive carbonyls, such as methylglyoxal, especially in diabetic conditions and the AGE products are considered the main cause of diabetes-related vascular complications." (PMID 29118444, 2017). "However, the ability of the brain to adapt to low glucose in insulin-injecting diabetes patients, to low oxygen in people at high altitude and increased ketone body in diet suggests that the brain makes use of more than one mechanism to acquire energy." (PMID 28154523, 2017). "Thus, the excessive breakdown of tissue proteins due to diminished insulin response as well as the unavailability of carbohydrate for energy metabolism in diabetes mellitus results in decreased body weight." (PMID 28077129, 2017). "Patients treated with insulin experienced higher diabetes distress compared to tablet- or diet-treated patients, and this emotional burden might cause insulin non-adherence if it is not improved." (PMID 28376921, 2017). "Following an FDR correction for multiple comparisons, three markers remained significantly associated at the <5% level with a higher odds of self-reported diabetes at baseline: insulin, glucose-dependent insulinotropic peptide (or gastric inhibitory polypeptide; GIP) and pancreatic polypeptide (PP)." (PMID 28753646, 2017). "In majority of the herbal products and secondary metabolites used in treating diabetes, the mechanisms of action involve regulation of insulin signaling pathways, translocation of GLUT-4 receptor and/or activation the PPARγ as well as anti-inflammatory and immunomodulatory action." (PMID 28729836, 2017). "Diabetes mellitus (DM) is a disorder of glucose metabolism that occurs due to either defect in insulin production by the pancreatic beta cells (type 1 DM) or resistance to insulin in the peripheral tissues (type 2 DM)." (PMID 28596971, 2017). "Presumably, astaxanthin may play an important role in the treatment of diabetes mellitus and hyperlipidemia by restoring insulin secretion and insulin sensitivity." (PMID 28632169, 2017). "Sufficient insulin secretion from pancreas beta cells is essential to maintain blood glucose within normal range, and destroy beta cells during T2D development upon insufficient insulin secretion and diabetes progression." (PMID 29988211, 2017). "Cyanidin also up-regulated the expression of the GLUT2, Kir6.2 and Cav1.2 genes that could have potential implications on glucose-induced insulin secretion, glucose homeostasis, and diabetes." (PMID 28788070, 2017).
diabetes (continued). "Diabetes is a metabolic and multifactorial disorder which is characterized by chronically increased levels of blood sugar and develops due to disturbed secretion and/or function of insulin." (PMID 28975089, 2017). "The need for insulin treatment is a clinical decision, while diabetes-associated autoantibodies are neither pathogenic nor categorical features of LADA." (PMID 28438156, 2017). "Despite the benefits of insulin therapy, many people with diabetes don’t adhere to treatment." (PMID 28680863, 2017). "Thus, the objectives of this study were to assess applicability, user acceptance, and effectiveness of InsuOnline for education of PCPs on insulin therapy for diabetes, as compared with a traditional onsite CME session with the same content and duration." (PMID 28279950, 2017). "Similarly, for the management of type-2 diabetes mellitus, insulin-lowering drugs should be privileged because insulin decreases the urine output of urate." (PMID 28669352, 2017). "Because tesamorelin, a stabilized GHRH analogue, has been previously shown to stimulate GH secretion in a physiological manner, this study was conducted in patients with type 2 diabetes to assess its potential effects on insulin sensitivity and diabetes control." (PMID 28617838, 2017). "Regardless of etiology, both forms of diabetes are underpinned by loss of glucose stimulated insulin secretion and concomitant hyperglycemia." (PMID 28424732, 2017). "Therefore, it is important to study β‐cell failure in type 2 diabetes mellitus and the impact of environment on islet response and impaired insulin secretion." (PMID 27009502, 2017). "Diabetes as an indicator of endocrine insufficiency was found on admission in 88 patients (38%) of the population under examination, of whom 37.5% were treated with insulin." (PMID 28207747, 2017). "Diabetes mellitus (DM) is characterized by hyperglycemia (high blood glucose levels) due to the inability of the pancreas to produce enough insulin or of the cells to respond to the insulin that is produced." (PMID 28045446, 2017). "The anabolic hormone insulin promotes postprandial storage of nutrients and tightly controls their consumption interprandially, thus playing a crucial homeostatic role, which becomes disrupted in obesity and diabetes." (PMID 29312008, 2017). "The biological activity of the insulin derivatives was tested on rats with experimental diabetes." (PMID 28296883, 2017). "At the time of their postoperative mammogram, 14 (18 %) had diabetes, with only 4 taking insulin." (PMID 27783370, 2017). "The management of diabetes patients needs to pay careful attention to the food they consume, to refer to nutritional tables, to apply precision in the preparation of portions and to constantly monitor calorie intake on the basis of insulin dosage." (PMID 28724422, 2017). "α2A‐adrenoceptor stimulation reduces insulin secretion from β‐islets [2171], with a polymorphism in the 5'‐UTR of the ADRA2A gene being associated with increased receptor expression in β‐islets and heightened susceptibility to diabetes [1673]." (PMID 29055040, 2017). "Moreover, peripheral insulin resistance often characterises pre-diabetes and involves failure of skeletal muscle to remove glucose from the bloodstream in response to insulin." (PMID 29042678, 2017). "A 56-year-old middle-eastern male with a long-standing history of poorly controlled type 2 diabetes mellitus presented to us complaining of severely painful bilateral upper and lower extremity cramps occurring shortly after his rapid-acting insulin analog injection(s)." (PMID 28993757, 2017). "However, varying patient pathways were found for people with diabetes especially if they required insulin." (PMID 28298226, 2017).
diabetes (continued). "Our description of ethnic differences in glucose, insulin, insulin sensitivity and insulin secretion before diabetes diagnosis supports the growing literature suggesting that there are important differences in the natural history of type 2 diabetes between South Asian and white individuals." (PMID 28409212, 2017). "Instead, pramlintide, as an amylin agonist with improved water solubility to reduce the amyloid propensity, was approved by the US Food and Drug Administration in April 2005 for bolus premeal administration adjunct to insulin therapy in patients with diabetes mellitus." (PMID 29029531, 2017). "This resulted in lethal diabetes, which required insulin treatment." (PMID 28270834, 2017). "Arsenic has been reported to cause injury to the pancreatic beta-cells and apoptosis, which may alter insulin production, function and may result in insulin dependent diabetes mellitus (IDDM) (Johnson and Luciani, 2010)." (PMID 29285009, 2017). "A sub-analysis of patients with diabetes in the prevention of restenosis with tranilast and its outcome (PRESTO) trial reported a significant risk reduction with metformin compared with insulin or sulphonylureas in major adverse cardiac events, myocardial infarction, and total deaths." (PMID 29017497, 2017). "In contrast, in a cohort of 339 critically ill patients (11% with a history of diabetes) with stress-hyperglycemia and markedly elevated c-peptide levels, intensive insulin therapy targeting normoglycemia reduced endogenous insulin secretion and normalized c-peptide levels." (PMID 28497374, 2017). "The association between insulin and diabetes was observed in the NHL study, but not the ovarian cancer study." (PMID 28753646, 2017). "Diabetes mellitus (DM) is a metabolic disease that affects more than 347 million people worldwide and is characterized by high blood glucose due to inadequate insulin production or insulin activity." (PMID 28981518, 2017). "Exposure to high traffic volume was shown to have a stronger impact among diabetic individuals on insulin, which could imply more complicated diabetes, expressing higher inflammatory profiles compared to those on oral hypoglycemic agents." (PMID 29194408, 2017). "Diabetes is a condition that affects the way one’s body reacts to insulin." (PMID 28772877, 2017). "Several groups of pharmaceutical agents are currently used for the treatment of diabetes via different mechanisms, such as stimulation of the release of insulin (e.g., sulfonylureas), reduction of hepatic glucose output and enhancement of the peripheral uptake of glucose (e.g. biguanidines)." (PMID 28770011, 2017). "The clinical presentation of the patient shares features of T1D (juvenile onset diabetes with acute onset and continuous insulin-treatment) and of ABCC8-mutated diabetes, including good control with relatively low insulin doses and no history of associated autoimmune disorders." (PMID 29112131, 2017). "A total of 40 individuals with diabetes (1.8% of early onset sub-group and 0.6% of adult onset sub-group) were carriers of known pathogenic missense variants in the GCK, HNF1A, HNF4A, ABCC8, and INS genes." (PMID 29207974, 2017). "Insulin-specific CD8 T cells are key for diabetes onset in both mouse and humans." (PMID 29259578, 2017). "Of the 6 patients with diabetes mellitus type 2, two patients were on insulin therapy." (PMID 27401737, 2017). "In a previous study, human ADSCs were differentiated into insulin-producing cells (IPCs) and transplanted into the mouse model of type 2 diabetes mellitus (T2DM), resulting in an increased level of circulating insulin and a subsequent improvement in metabolic parameters and blood glucose reduction." (PMID 28303247, 2017). "Diabetes-associated metabolic disorders manifest as hyperglycemia and increased advanced glycated hemoglobin (HbA1c) through disturbances of insulin secretion or action efficiency, and these disorders play a central role in diabetes clinical care and pathophysiology." (PMID 29216237, 2017).